IL21 (interleukin 21)
Diseases named in the same sentence as IL21 in open-access papers (continued):
Sharing a sentence is not in itself a finding about the gene and the disease.
HIV-1 infection (11 papers, 2015 to 2025). The type species of lentivirus and the etiologic agent of acquired immunodeficiency syndrome (AIDS). "Notably, exogenous IL-21 limits early HIV-1 infection in humanized mice, and lower viremia in vivo is associated with higher miR-29 expression." (PMID 26108174, 2015). "It has been shown that increasing IL-21 production or using exogenous methods of increasing cellular IL-21 production can limit the extent of initial HIV-1 infection." (PMID 39940691, 2025). "Concretely, enhanced lipophagy leads to fuel mitochondrial metabolism due to glutaminolysis and restores protective CD8A T-cell immunity during persistent HIV-1 infection in an IL-21-dependent manner." (PMID 35514981, 2022). "Some studies have shown that exogenous methods to increase IL-21 production or increase cellular IL-21 production can limit the degree of initial HIV-1 infection." (PMID 34383171, 2021). "These cells were also the most permissive to HIV-1 infection and are the main source of IL-21 after in vitro stimulation in contrast to CXCR3− TFH cells." (PMID 26034905, 2015). "Together, these findings suggest for the first time the ability of IL-21 to directly suppress HIV-1 infection in CD4 T cells." (PMID 26108174, 2015). "We report that IL-21 suppresses initial HIV-1 infection in lymphoid CD4 T cells and this antiviral activity was rapid, independent of cytotoxic effector T cells, but requires induction of cell-intrinsic miR-29." (PMID 26108174, 2015). "Together, these findings reveal a novel antiviral IL-21-miR-29 axis that promotes CD4 T-cell-intrinsic resistance to HIV-1 infection, and suggest a role for IL-21 in initial HIV-1 control in vivo." (PMID 26108174, 2015). "In this study, we report a novel antiviral activity of IL-21 that is mediated by miR-29 and results in suppressed HIV-1 infection in primary lymphoid CD4 T cells." (PMID 26108174, 2015). "Consistent with this antiviral activity, we find that exogenous IL-21 administration limits both the incidence and magnitude of primary HIV-1 infection in vivo in humanized mice." (PMID 26108174, 2015). "We took advantage of this system to assess the effect of IL-21 on primary HIV-1 infections in HLACs prepared from freshly excised human splenic tissues." (PMID 26108174, 2015). "Taken together, these results implicate an IL-21–miR-29 axis in direct HIV-1 suppression in CD4 T cells and suggest that pretreatment with IL-21 can limit the magnitude of the initial HIV-1 infection in vivo." (PMID 26108174, 2015). "Compared with control-LNA antagomirs, mir-29-LNA antagomirs significantly abrogated the ability of IL-21 to inhibit HIV-1 infection in CD4 T cells, indicating that the antiviral activity of IL-21 was at least in part mediated by miR-29." (PMID 26108174, 2015). "Collectively, these findings demonstrate a novel and rapid miR-29-mediated antiviral activity of IL-21 that acts through STAT3 in target CD4 T cells to limit initial HIV-1 infection." (PMID 26108174, 2015). "Specifically, the recovery of the Th17 compartment, which is severely and permanently damaged during HIV-1 infection, might benefit from therapies including IL-21 treatment, manipulation of IDO1-mediated Trp metabolism, or microbiome-targeted interventions." (PMID 39842407, 2025). "Exogenously increasing IL-21 or promoting pre-existing IL-21 cell pools may help stimulate immune resistance to the initial HIV-1 infection." (PMID 41327829, 2025). "Interestingly, HIV-1-specific CD8+ T cells can express IL-21 after primary infection and the IL-21-expressing cell population is expanded in individuals referred to as elite controllers of HIV-1 infection." (PMID 31183385, 2019). "Our observation that γc cytokines, specifically IL-2, IL-7, IL-15, and IL-21 were potent inducers of Tim-3 expression on T cells in the antigen-independent manner in HBV infection were consistent with the role of these cytokines in HIV-1 infection." (PMID 28401068, 2017).
HIV-1 infection (continued). "Thus, we considered the humanized BLT mice a useful model to interrogate the in vivo role of IL-21 in HIV-1 infection." (PMID 26108174, 2015). "Finally, we sought to investigate the effect of exogenous IL-21 treatment on primary HIV-1 infection in vivo." (PMID 26108174, 2015). "Notably, we found that lower HIV-1 infection in IL-21-treated HLACs resulted in improved CD4/CD8 T-cell ratio (less CD4 depletion) in these cultures." (PMID 26108174, 2015). "Abrogation of IL-21-mediated miR-29 induction on STAT3 blockade coupled with enriched STAT3 binding to putative regulatory sites within MIR29 genes support STAT3 as a positive regulator of miR-29 expression in CD4 T cells during HIV-1 infection." (PMID 26108174, 2015). "Notably, HIV-1 titres inversely correlated with plasma IL-21 levels, supporting a protective role for IL-21 against very early HIV-1 infection." (PMID 26108174, 2015). "Because IL-21 impaired HIV-1 infection when administered before or after viral exposure, we asked whether it can reverse HIV-1-associated downregulation of miR-29." (PMID 26108174, 2015). "IL-21 suppressed HIV-1 infection whether added before HIV-1 inoculation or added to HLACs after HIV-1 inoculation and extensive washing to remove viral supernatants." (PMID 26108174, 2015). "Interestingly, we found that HIV-1 infection (as measured by GFP+CD3+) of CD4 T cells in IL-21-treated HLACs was significantly reduced compared with untreated cultures." (PMID 26108174, 2015). "Interestingly, we found that humanized mice treated with exogenous IL-21 were largely protected from early HIV-1 infection and reduced viral load in these animals correlated with higher miR-29 expression in splenic CD4 T cells." (PMID 26108174, 2015). "Notably, compilation of X4-HIV-1 infection across multiple donors revealed marked suppression of HIV-1 infection by IL-21 (median suppression=68%, n=12; P<0.0005, Wilcoxon signed-rank test)." (PMID 26108174, 2015). "However, future work in experimental animal models that allow genetic ablation or depletion of IL-21/STAT3 before HIV-1 infection will be required to more precisely define the in vivo activity of IL-21 at early stages of lentiviral infections." (PMID 26108174, 2015). "Importantly, the ability of IL-21 to overcome HIV-1-induced miR-29 downregulation was consistent with its ability to also suppress HIV-1 infection when added to HLACs after CD4 T cells have been infected with HIV-1." (PMID 26108174, 2015). "However, the correlation between the elevated level of ICOS+cTfh or IL-21+ICOS+cTfh cells with memory B cell subsets during acute HIV-1 infection stage in our results indicated that signaling via ICOS after cTfh activation may drive the memory B cell perturbation as early as primary infection stage." (PMID 35222430, 2022). "Our preceding results strongly supported a significant contribution of an IL-21–miR-29 axis in HIV-1 control prompting us to next determine the relationship between miR-29 and HIV-1 infection in human subjects." (PMID 26108174, 2015). "We also observed a similar result that the negative association trends between the frequency of IL-21+ICOS+cTfh cells and CD4+T cell count in both acute and chronic HIV-1 infection stage." (PMID 35222430, 2022). "The expansion of TLM and PBs may be the synergism of ICOS+cTfh or IL-21+ICOS+cTfh cells with other factors, such as immune activation and chronic inflammation after HIV-1 infection." (PMID 35222430, 2022). "IL-21 inhibited both R5- and X4-tropic HIV-1 infection, and did not alter surface expression of the HIV entry coreceptors CD4, CCR5 or CXCR4 on CD4 T cells, suggesting that the antiviral mechanism of IL-21 likely involved post-entry events." (PMID 26108174, 2015). "Association analyses showed that the levels of ICOS+cTfh and IL-21+ICOS+cTfh cells were negatively correlated with those of AM, CM, RM cells, and positively correlated with those of NM cells in AHI but not chronic HIV-1 infection stage (CHI)." (PMID 35222430, 2022).
HIV-1 infection (continued). "HIV-1 infection was equivalently suppressed by IL-21 even in the absence of NK, NKT and CD8 T cells, indicating that the observed antiviral activity of IL-21 did not depend on these cells but likely a direct effect on HIV-1 permissive CD4 T cells." (PMID 26108174, 2015).
lung cancer (11 papers, 2017 to 2025). A malignant neoplasm involving the lung. "Apart from Th1 cells, other subpopulations, in particular Th9 cells (producing IL-9 and IL-21) and Th17 cells (producing IL-17), have been implicated in lung cancer." (PMID 36776832, 2023). "Researchers have reported that IL-21 expression significantly enhances the cytotoxicity of NKG2D CAR-NK cells against lung cancer cells in a dose-dependent manner." (PMID 40705122, 2025). "The expression of IL-21 was shown to enhance the cytotoxicity of NKG2D CAR-NK cells against lung cancer cells in a dose-dependent manner, thereby inhibiting tumor growth both in vitro and in vivo." (PMID 41301424, 2025). "In a recent study, CAR-NK cells coexpressing NKG2D and IL-21 were established, and their efficacy in treating lung cancer was evaluated both in vitro and in vivo." (PMID 40705122, 2025). "For example, the expression of interleukin-21 (IL-21) significantly enhanced the cytotoxicity of NKG2D CAR-NK cells towards lung cancer cells in a dose-dependent manner, and effectively inhibited tumor growth in vitro and in vivo." (PMID 39950266, 2025). "We established CAR-NK cells by co-expressing natural killer group 2 member D (NKG2D) and IL-21, and evaluated the efficacy of NKG2D-IL-21 CAR-NK cells in treating lung cancer in vitro and in vivo." (PMID 38263004, 2024). "In this study, we constructed NK-92 cells expressing NKG2D and IL-21 to investigate if efficacy against lung cancer." (PMID 38263004, 2024). "Our data suggested that the expression of IL-21 effectively increased the cytotoxicity of NKG2D CAR-NK cells against lung cancer cells in a dose-dependent manner and suppressed tumor growth in vitro and in vivo." (PMID 38263004, 2024). "In addition, the higher the expression of IL-21 is, the higher the survival rate of lung cancer patients." (PMID 38263004, 2024). "In addition to IL-17, Th17 cells produce other proinflammatory cytokines such as IL-21, IL-22, and IL-26, which are also related with lung cancer." (PMID 36776832, 2023). "Accordingly, the addition of IL-21 to these cultures also counteracted the marked inhibition of T cell proliferation observed in the presence of supernatants from cell lines representing colon and lung cancers." (PMID 28239749, 2017). "By looking into the mechanism we found that consistent with the presence of Th9 cells in the tumor of NSCLC patients, targeted deletion of IL-9 resulted in significant upregulation of IL-21, a cytokine produced by Th9 cells that may regulate anti-tumor effects of Th9 cells in lung cancer." (PMID 35514957, 2022).
metastatic melanoma (11 papers, 2008 to 2025). A melanoma that has spread from its primary site to another anatomic site. "A Phase II study in metastatic melanoma patients confirmed the biological activity of IL-21, with 9 of 40 patients showing partial remission and 16 showing stable disease." (PMID 40376002, 2025). "In patients with metastatic melanoma and renal cell carcinoma, intravenous infusion of recombinant human IL-21 resulted in upregulation of perforin and granzyme B mRNA levels in CD8 T cells and NK cells." (PMID 40376002, 2025). "A preliminary report showed that, in spite of earlier encouraging results, IL-21 activity in metastatic melanoma is comparable to that of DTIC." (PMID 25961061, 2015). "In humans, a phase II trial of IL-21 monotherapy as first line treatment for patients with limited-disease metastatic melanoma demonstrated 25% OR with 9 partial responses, a PFS of 4.3 months and median OS of 12.4 months indicating that IL-21 has anti-tumour effects as a single agent." (PMID 34960140, 2021). "A phase II trial of iv IL-21 was then conducted in 40 patients with metastatic melanoma." (PMID 25961061, 2015). "Conversely, immune activation via homeostatic proliferation is important for the rejection of tumors and IL-21 administration may inhibit the progression of metastatic melanoma and renal carcinoma in clinical protocols." (PMID 18773086, 2008). "A phase I study involving IL-21 monotherapy for metastatic melanoma or renal cell carcinoma reported that monotherapy was well tolerated and exhibited anti-tumour activity in some patients, thereby suggesting that IL-21 may have an anti-tumour effect as a monotherapy." (PMID 20029417, 2010). "Another study on metastatic melanoma patients showed that IL-21-induced polyclonal CTL, in combination with CTLA4 blockade, controlled refractory metastatic melanoma." (PMID 40376002, 2025). "IL-21 use had also shown efficacy in metastatic melanoma, but direct administration of IL-21 is no longer a standard practice due to adverse inflammatory effects and a lack of consistent clinical data." (PMID 36676129, 2023). "A phase I/IIa study of intravenous (iv) rIL-21, conducted in metastatic melanoma, showed that IL-21 does not induce vascular-leak syndrome by repeated iv infusion." (PMID 25961061, 2015). "Indeed, although IL-18 and IL-21 have not been evaluated in EOC patients, these cytokines as single agents showed limited clinical benefit in the setting of metastatic melanoma." (PMID 21203522, 2010).
parasitemia (11 papers, 2011 to 2026). "In recent years, the IL-21/IL-21R signaling axis has been implicated in the regulation of immunity and the pathogenesis in several bacterial, viral, fungal, and parasitic infections." (PMID 31867283, 2019). "Mice deficient for either IL-21 (Il21−/−) or IL-21R (Il21r−/−) showed significantly reduced inflammatory responses following parasitic infections as compared with their WT counterparts." (PMID 31867283, 2019). "It was reported that IL-21 is highly expressed in parasitized organs of infected humans as well as in murine models of human parasitic diseases." (PMID 40586570, 2025). "In the limited research examining the temporal role of IL-21 during parasitic infections, this cytokine appears to play opposing roles in supporting antibody production at early and late time points post-infection." (PMID 35631044, 2022). "T cell-derived IL-21 has been shown to act on B cells during Pcc infection to promote control of chronic parasitemia and the formation of antigen-specific MBC populations in the spleen, as well as long-lived, bone marrow B220+CD138hi plasmablasts." (PMID 35631044, 2022). "Previous work on the immune response to P. chabaudi shows that IFN-γ controls the height of the peak of parasitemia, whereas Tfh and IL-21 are required for antibodies to eliminate the parasite." (PMID 32634740, 2020). "In Plasmodium chabaudi infection, IFN-γ+ T cells control parasitemia, whereas antibody and IL-21+Bcl6+ T cells effect final clearance, suggesting an evolutionary driver for the hybrid population." (PMID 32634740, 2020). "IL-21 is a pleiotropic cytokine whose functions in protection and immunopathology during parasitic diseases have been explored in limited ways." (PMID 31867283, 2019). "IL-21 and its cognate receptor, IL-21R, are highly expressed in parasitized organs of infected humans as well in murine models of the human parasitic diseases." (PMID 31867283, 2019). "The IL-21/IL-21R axis disruption also led to impaired resolution of parasitemia in the chronic phase of infection." (PMID 31867283, 2019). "It has been suggested that the roles played by the IL-21/IL-21R signaling axis is context-dependent during microbial infections, including parasitic infections." (PMID 31867283, 2019). "These high parasitemias were maintained in both Il21-/- and Il21r-/- after 120–150 days of infection (44±4% in Il21-/- and 56±3% in Il21r-/- mice at day 120 post-infection), without mortality." (PMID 25763578, 2015). "Similar to WT C57BL/6 mice, both Il21-/- and Il21r-/- mice had very low parasitemias by 11–14 days post-infection." (PMID 25763578, 2015). "Notably, few studies have examined the role of IL-21 outside the context of immune response initiation during parasitic infections." (PMID 35631044, 2022). "Most studies investigating the roles played by the IL-21/IL-21R axis in parasitic infections, whether protective or detrimental, stemmed from reports in animal models." (PMID 31867283, 2019). "Unveiling the IL-21/IL-21R crosstalk with other cytokine networks and their downstream genes will provide insight into the development of novel therapeutic targets for the parasite-induced immunopathology and the control of parasitic infections." (PMID 31867283, 2019). "The presence of large numbers of Ter119+ rbc in the spleens of Il21-/- and Il21r-/- mice indicates increased hematopoiesis in response to anemia, presumably leading to production of many new rbc, which then controls the level of parasitemia." (PMID 25763578, 2015). "The higher variability in the parasitemias in these mixed BM chimeric mice compared to Il21r-/- late in infection may reflect B-cell-independent alternate mechanisms, which require IL-21." (PMID 25763578, 2015). "The impaired control of parasitemia and loss of the humoral response to P. chabaudi in Il21-/- and Il21r-/- mice were not due to lack of development of phenotypically-defined Tfh cells." (PMID 25763578, 2015).